RNU7-171P (RNA, U7 small nuclear 171 pseudogene)
Gene: Small nuclear RNA gene on chromosome 9 (128,543,916 to 128,543,977, forward strand). Ensembl gene ENSG00000238406.
Homologues: Orthologues: macaque U7 (89% identical). Paralogues in human: RNU7-60P (89% identical), RNU7-67P (87% identical), RNU7-52P (85% identical), RNU7-57P (85% identical), RNU7-12P (84% identical), RNU7-13P (84% identical), RNU7-35P (84% identical), U7 (84% identical), RNU7-11P (82% identical), RNU7-160P (82% identical), RNU7-29P (82% identical), RNU7-30P (82% identical), and 142 more.